ACO1 (aconitase 1)
Description:
Bifunctional iron sensor that switches between 2 activities depending on iron availability. Iron deprivation, promotes its mRNA binding activity through which it regulates the expression of genes involved in iron uptake, sequestration and utilization. Binds to iron-responsive elements (IRES) in the untranslated region of target mRNAs preventing for instance the translation of ferritin and aminolevulinic acid synthase and stabilizing the transferrin receptor mRNA. Conversely, when cellular iron levels are high, binds a 4Fe-4S cluster which precludes RNA binding activity and promotes the aconitase activity, the isomerization of citrate to isocitrate via cis-aconitate.
Synonyms: IRP1; IREB1; IREBP; ACONS; HEL60; IREBP1
Tractability: Small molecule: a structure with a bound ligand is known. PROTAC: ubiquitination databases record sites on it; its protein half-life has been measured.
Gene: Protein-coding gene on chromosome 9 (32,384,603 to 32,454,769, forward strand). Ensembl gene ENSG00000122729.
Subcellular location: Cytoplasm, cytosol
Subcellular location (Human Protein Atlas): Cytosol; Mitochondria
Pathways (Reactome):
Metabolism: NADPH regeneration
Transport of small molecules: Iron uptake and transport
Gene Ontology:
Molecular function: 3 iron, 4 sulfur cluster binding; 4 iron, 4 sulfur cluster binding; aconitate hydratase activity; iron-responsive element binding; iron-sulfur cluster binding; mRNA regulatory element binding translation repressor activity; protein binding; RNA binding
Biological process: citrate metabolic process; response to iron(II) ion; intracellular iron ion homeostasis; NADPH regeneration; negative regulation of translation
Cellular component: cytoplasm; cytosol; endoplasmic reticulum; extracellular exosome; Golgi apparatus
Genetic constraint (gnomAD): Loss-of-function variants: 63 observed, 92.56 expected, observed/expected ratio (o/e) 0.68, 90% interval 0.56 to 0.84. The upper end of that interval is the gene's LOEUF score, 0.84, which puts it in group 3 of 6, group 1 being the genes least tolerant of losing a copy. Missense variants: 880 observed, 1,069.4 expected, observed/expected ratio (o/e) 0.82, 90% interval 0.78 to 0.87. Synonymous variants: 345 observed, 391.01 expected, observed/expected ratio (o/e) 0.88, 90% interval 0.81 to 0.96.
Homologues: Orthologues: chimpanzee ACO1 (99% identical), macaque ACO1 (99% identical), pig ACO1 (95% identical), rabbit ACO1 (94% identical), mouse Aco1 (93% identical), rat Aco1 (93% identical), guinea pig ACO1 (93% identical), tropical clawed frog aco1 (85% identical), zebrafish aco1 (81% identical). Paralogues in human: IREB2 (61% identical), ACO2 (26% identical).
Diseases named in the same sentence as ACO1 in open-access papers:
ACO1 is named in the same sentence as 95 diseases in open-access papers, as found by Europe PMC text mining. Sharing a sentence is not in itself a finding about the gene and the disease. The quoted sentences say what the papers report.
iron deficiency (23 papers, 2009 to 2025). "During iron deficiency, iron regulatory proteins (ACO1/IRP1, IREB2/IRP2) increase iron levels by binding to a small subset of mRNA transcripts that harbor an iron responsive element (IRE) to modulate their translation." (PMID 29291011, 2017). "During cellular iron deficiency, IREB2 and ACO1 induce iron acquisition and retention by stabilising mRNAs that encode iron uptake proteins such as TFRC while blocking translation of mRNAs that encode proteins involved in iron sequestration and egress." (PMID 34880854, 2021).
polycythemia (18 papers, 2014 to 2026). Abnormally high mass or concentration of red blood cells in the blood, either due to an increase in erythropoiesis or a decrease in plasma volume. "We tested the eight hemoglobin associated variants at the ACO1 locus for association with anemia and polycythemia (five phenotypes), seven blood cell indices, and five iron biomarkers, resulting in a total of 136 (eight times 17) tests and we found 23 associations (P value < 0.05/136 = 3.7 × 10−4)." (PMID 32327693, 2020).
breast cancer (12 papers, 2017 to 2024). A primary or metastatic malignant neoplasm involving the breast. "We constructed a risk model based on the expression levels of these RBPs and found that ADAT2, C2orf15, SRP72, PAICS, RBMS3, APOBEC3G, NOA1, and ACO1 could be used for risk assessment in terms of breast cancer prognosis." (PMID 38783078, 2024). "ACO1, as one of immune-related prognostic signatures, was used for foreseeing the prognosis of breast cancer or endometrial cancer patients." (PMID 36059676, 2022). "The results demonstrated that ACO1, DPP4, HMOX1, and TFRC were significantly associated with breast cancer grades (all p < 0.05)." (PMID 35154262, 2021). "Conversely, knockdown or knockout of MEMO1 in breast cancer cells resulted in a statistically significant decrease in the expression levels of TFR1, TFR2, ACO1, and SLC25A28." (PMID 38640016, 2024). "Consistently, multiple studies have shown the ectopic expression of ACO1 and IREB2 in several types of solid cancer, including lung cancer, breast cancer, and prostate cancer." (PMID 36059676, 2022). "By further analysing above EMT-related RBPs and AS in breast cancer tissues in TCGA, it was found that the expression levels of ADAT2, C2orf15, SRP72, PAICS, RBMS3, APOBEC3G, NOA1, ACO1 and the AS of TNC and COL6A3 were significantly correlated with the prognosis of breast cancer patients." (PMID 38783078, 2024). "Analyzing these genes individually, we found that Aco1 is significantly correlated with worse overall patient survival in all breast cancer patients (HR = 1.56, p = 0.00014), and TNBC patients had even worse outcomes when stratified by Aco1 expression (HR = 4.22, p = 0.0041)." (PMID 39262774, 2024). "ACO1, SLC25A28, and PLOD1 showed GOF interactions with MEMO1 in breast cancer cells." (PMID 38640016, 2024). "Besides, inosine supplementary stimulates the synthesis of nascent TCA cycle enzymes, including citrate synthesis (CS) and aconitase 1 (ACO1), to further enhance oxidative phosphorylation of breast cancer cells under glucose starvation, leading to the accumulation of iso-citric acid." (PMID 37532694, 2023). "Remarkably, ACO1 knockdown only inhibited proliferation of the high-MEMO1 cells, but not MEMO1 knockout breast cancer cells, while SLC25A28 and PLOD1 knockdowns showed some effect in all cell lines, but a stronger inhibition in the high-MEMO1 cells than in MEMO1 knockout." (PMID 38640016, 2024).
anemia (9 papers, 2011 to 2025). A reduction in the number of red blood cells, the amount of hemoglobin, and/or the volume of packed red blood cells. "Also known as iron regulatory element binding protein 1 (IREB1), ACO1 regulates cellular iron homeostasis and is linked to anemia in human." (PMID 25765547, 2015). "Constitutive RNA-binding activity presumably leads to anemia through binding of ACO1 to the IRE elements of one or more of IRE containing transcripts, involved in erythropoiesis, and affecting their translation." (PMID 32327693, 2020).
hepatocellular carcinoma (6 papers, 2020 to 2023). A malignant tumor that arises from hepatocytes. "ACO1, also known as IRP1, is an RNA-binding protein that controls iron homeostasis by regulating TFRC and FTH1 expression in CCA and hepatocellular carcinoma." (PMID 36733386, 2022).
melanoma (6 papers, 2021 to 2025). A malignant, usually aggressive tumor composed of atypical, neoplastic melanocytes. "ACO1 depletion decreased iron levels and suppressed erastin- and RSL3-induced ferroptosis in melanoma." (PMID 36733386, 2022). "In fact, ACO1 and PLOD1 displayed LOF interactions in melanoma." (PMID 38640016, 2024).
Parkinson disease (5 papers, 2014 to 2025). A progressive degenerative disorder of the central nervous system characterized by loss of dopamine producing neurons in the substantia nigra and the presence of Lewy bodies in the substantia nigra and locus coeruleus. "The IRP1 gene (ACO1) has been associated with cutaneous malignant melanoma and neuropathic pain in HIV-infected patients, while the IRE-binding activity of IRP1 was reported to be increased in Friedreichs' ataxia and in Parkinson's disease." (PMID 25120486, 2014). "Aconitase 1 (ACO1) links oxidative stress and iron accumulation in Parkinson’s disease (PD)." (PMID 36670874, 2022).
Lung Fibrosis (4 papers, 2021 to 2023). "Among them, ACO1 is associated with pulmonary fibrosis, and cytoplasmic aconitase 1/ iron regulatory protein 1 (ACO1/IRP1), a bifunctional protein expressed in the cytoplasm, played a role in regulating iron homeostasis in cells." (PMID 36672671, 2023). "This suggests that ACO1 facilitates alveolar regeneration in BLM-induced lung fibrosis in mice." (PMID 35910393, 2022). "In this regard, it is interesting to note that the lncRNA FENDRR (FOXF1-adjacent non-coding developmental regulatory RNA) sequesters miR-214 while interacting with ACO1 (aconitase 1, also known as IRP1) to decrease cellular iron concentration and reduce pulmonary fibrosis." (PMID 35893236, 2022).
renal carcinoma (3 papers, 2014 to 2024). A carcinoma arising from the epithelium of the renal parenchyma or the renal pelvis. "Here, we report a novel founding that low ACO1 and IREB2 contents in renal cancer are linked to the decreased invasion of B cells, neutrophils, CD4+ T cells, dendritic cells, and CD8+ T cells, along with macrophages." (PMID 36059676, 2022). "ACO1 antagonist sodium oxalomalate (OMA) and IREB2 inhibitor sodium nitroprusside (SNP) was used to treat renal cancer ACHN cells together with sorafenib." (PMID 36059676, 2022). "Meanwhile, there is a paucity of information about the mechanisms and clinical significance of ACO1 and IREB2 downregulation in renal cancers." (PMID 36059676, 2022). "Weak evidence has revealed the role and clinical aspects of ACO1 and IREB2 in renal cancer at various stages of etiology and prognosis based on the strong relationship between iron homeostasis and carcinogenesis." (PMID 36059676, 2022). "The protein expression level of ACO1 and IREB2 were further investigated in renal cancer using the HPA database, and we noticed that the ACO1 and IREB2 protein level turned evidently down in the tissues of KIRC contrasted with healthy kidney." (PMID 36059676, 2022). "ACO1 and IREB2 downregulation in renal cancers were correlated with cancer aggressiveness, cellular iron homeostasis, cytotoxic immune cell infiltration, and patient survival outcomes." (PMID 36059676, 2022). "More remarkably, ACO1 and IREB2 regulate the time of survival of individuals with renal cancer partly through immune cell invasion." (PMID 36059676, 2022). "We then wondered if blocking ACO1 and IREB2 action interferes with sorafenib-triggered cell death in renal cancer." (PMID 36059676, 2022). "The current work focuses on combining several bioinformatics tools to assess if ACO1 and IREB2 are involved in renal cancer development and ferroptosis, as well as their molecular regulation." (PMID 36059676, 2022). "Herein, blocking the activation of ACO1 or IREB2 by its inhibitors OMA or SNP ameliorated sorafenib-triggered cell death, supporting that ACO1 and IREB2 could participate in its cytotoxic influence on renal cancer cells." (PMID 36059676, 2022). "As far as we know, the network between ACO1, IREB2 and immune cell invasion in renal cancer has not been clearly studied." (PMID 36059676, 2022).
age-related macular degeneration (2 papers, 2012 to 2014). Age-related loss of vision in the central portion of the retina (macula), secondary to retinal degeneration. "Finally, polymorphisms in both ACO1 and IREB2 have been linked to age-related macular degeneration." (PMID 25120486, 2014).
COVID-19 (2 papers, 2021 to 2024). A disease caused by infection with severe acute respiratory syndrome coronavirus 2. "Here, we observe over-expression of CC2D2A, HFE, and ACO1 in COVID-19 infections and lower expression in non-COVID-19 previously circulating infections." (PMID 33437935, 2021). "Interestingly, ACO1 is involved in iron metabolism, and heme appears to be interlinked with COVID-19 pathophysiology." (PMID 33437935, 2021). "ACO1 was over-expressed in COVID-19 versus HC and under-expressed in non-COVID-19 viral infections versus HC, whereas ATL3 entirely oppositely regulated." (PMID 33437935, 2021).
lung carcinoma (2 papers, 2014 to 2022). "In addition, ACO1 and IREB2 were identified to be required for erastin-induced ferroptosis in lung cancer cells." (PMID 36059676, 2022).
ovarian carcinoma (2 papers, 2015 to 2023). A malignant neoplasm originating from the surface ovarian epithelium. "Furthermore, lower expression levels of ACO1, HFE, IREB2, and MTF1 in iron regulation were associated with an advanced stage of ovarian cancer." (PMID 38186569, 2023). "Exploring the iron regulation in ovarian cancer, most genes integral to this process, like IREB2, HFE, BMP6, HMOX1, and ACO1, showed decreased expression compared to their normal tissue counterparts." (PMID 38186569, 2023).
breast tumour (1 paper, 2012). "Genes associated with the cardiotoxicity of doxorubicin (through negative effects on mitochondrial function when converted to doxorubicinol) also have altered expression in breast tumour cells upon selection for doxorubicin resistance, including ACO1, ATPS, CYCS, and ATP2B4." (PMID 22938713, 2012).
chronic lung disease (1 paper, 2022). According to the definitions of the American and British Thoracic Societies, including pulmonary functional tests, X-rays, and CT scans for items such as fibrosis, bronchiectasis, bullae, emphysema, nodular or lymphomatous abnormalities. "The expression of ACO1 in IPF vs. other chronic lung diseases was investigated by western blotting since IPF displays abnormal remodeling in parenchyma as well as in the interstitium." (PMID 35910393, 2022). "The data presented in this study demonstrate that the specific expression patterns of ACO1 in fibrotic areas of IPF lungs, as manifested by immunohistochemical staining, are not observed in non-IPF chronic lung diseases." (PMID 35910393, 2022).
gastric cancer (1 paper, 2019). A primary or metastatic malignant neoplasm involving the stomach. "Decreased expression of aconitase, encoded by ACO1 and ACO2, is described for many types of tumor cells, and represents an unfavorable prognostic marker in gastric cancer." (PMID 30967137, 2019).
glioma (1 paper, 2017). A benign or malignant brain and spinal cord tumor that arises from glial cells (astrocytes, oligodendrocytes, ependymal cells). "CS and aconitase (ACO1/2), enzymes that function upstream of citrate oxidation, were expressed at higher levels in IDH1MUT glioma than in IDH1WT glioma." (PMID 28467784, 2017).
malaria (1 paper, 2024). Malaria is a serious and sometimes fatal disease caused by a parasite that commonly infects a certain type of mosquito which feeds on humans. "The downregulation of ACO1 was primarily enriched in pathways related to Primary Immunodeficiency, Phototransduction, Mucin-type O-glycan Biosynthesis, and Malaria." (PMID 39735537, 2024).
normocytic anemia (1 paper, 2020). Anemia in which the red blood cell volume is normal. "Taken together, these data show that Cys506Ser is a gain-of-function mutation that generates an ACO1 protein with constitutively active RNA-binding function leading to normocytic anemia in humans." (PMID 32327693, 2020).
periodontal disease (1 paper, 2025). "Given these connections, ACO1 may play a shared role in the pathogenesis of both periodontal disease and COPD through its regulation of iron metabolism." (PMID 41009972, 2025).
sarcoma (1 paper, 2021). A usually aggressive malignant neoplasm of the soft tissue or bone. "The results showed that fused in sarcoma (FUS), aconitase 1 (ACO1), and YTH domain containing 1 (YTHDC1) motifs have specific miR-18b binding sites." (PMID 34853307, 2021).
steatosis (1 paper, 2025). Increased lipid within the cytoplasm of cells. "Therefore, the suppressed expression of CPT1 and ACO1 in the HF group indicates reduced mitochondrial and peroxisomal fatty acid oxidation, contributing to hepatic lipid accumulation and steatosis." (PMID 40872133, 2025).
thyroid cancer (1 paper, 2025). "Notably, genes such as B4GALT1, ALDH1A1, NDUFV2, and ACO1 had mutations in 6% of samples, making them frequent mutational targets in thyroid cancer." (PMID 40861812, 2025).